ADAMTS14 (ADAM metallopeptidase with thrombospondin type 1 motif 14)
Description:
Has aminoprocollagen type I processing activity in the absence of ADAMTS2. Seems to be synthesized as a latent enzyme that requires activation to display aminoprocollagen peptidase activity. Cleaves lysyl oxidase LOX at a site downstream of its propeptide cleavage site to produce a short LOX form.
Tractability: Antibody: its Gene Ontology location is reachable by antibodies, with high confidence; UniProt places it where antibodies can reach, with medium confidence; UniProt predicts a signal peptide or a membrane-spanning region.
Gene: Protein-coding gene on chromosome 10 (70,672,367 to 70,762,441, forward strand). Ensembl gene ENSG00000138316.
Subcellular location: Secreted, extracellular space, extracellular matrix
Subcellular location (Human Protein Atlas): Golgi apparatus; Vesicles; Predicted to be secreted
Pathways (Reactome):
Disease: Defective B3GALTL causes PpS
Extracellular matrix organization: Collagen biosynthesis and modifying enzymes
Metabolism of proteins: O-glycosylation of TSR domain-containing proteins
Gene Ontology:
Molecular function: metalloendopeptidase activity; metallopeptidase activity
Biological process: collagen fibril organization; extracellular matrix organization; proteolysis
Cellular component: extracellular matrix; extracellular region
Genetic constraint (gnomAD): Loss-of-function variants: 98 observed, 120 expected, observed/expected ratio (o/e) 0.82, 90% interval 0.69 to 0.97. The upper end of that interval is the gene's LOEUF score, 0.97, which puts it in group 4 of 6, group 1 being the genes least tolerant of losing a copy. Missense variants: 1,558 observed, 1,647.8 expected, observed/expected ratio (o/e) 0.95, 90% interval 0.91 to 0.99. Synonymous variants: 664 observed, 653.75 expected, observed/expected ratio (o/e) 1.02, 90% interval 0.95 to 1.08.
Homologues: Orthologues: chimpanzee ADAMTS14 (99% identical), macaque ADAMTS14 (97% identical), dog ADAMTS14 (88% identical), pig ADAMTS14 (87% identical), guinea pig ADAMTS14 (83% identical), rat Adamts14 (82% identical), mouse Adamts14 (81% identical), rabbit ADAMTS14 (81% identical), tropical clawed frog adamts14 (62% identical), zebrafish adamts14 (41% identical). Paralogues in human: ADAMTS3 (54% identical), ADAMTS2 (50% identical), ADAMTS18 (28% identical), ADAMTS7 (28% identical), ADAMTS16 (27% identical), ADAMTS9 (27% identical), ADAMTS10 (26% identical), ADAMTS6 (26% identical), ADAMTS20 (26% identical), ADAMTS12 (26% identical), ADAMTS17 (25% identical), ADAMTS19 (24% identical), and 13 more.